CARD14 (caspase recruitment domain family member 14)
Diseases named in the same sentence as CARD14 in open-access papers (continued):
Sharing a sentence is not in itself a finding about the gene and the disease.
psoriasis (continued). "Given these associations, we hypothesized that CARD14 rs34367357 might influence not only the onset of psoriasis but also the response to biologic therapies." (PMID 41010661, 2025). "Although these findings require confirmation in larger cohorts, they raise the possibility that the timing of treatment initiation could be an important consideration in optimizing outcomes for patients with psoriasis carrying CARD14 mutations." (PMID 41010661, 2025). "However, CARD14 signaling has so far been almost exclusively studied in skin, where several gain-of-function CARD14 mutations have been associated with psoriasis." (PMID 41131424, 2025). "In addition, a common variant of CARD14 (c.C2458T/p.R820W) exceeds genome-wide significance for association with psoriasis, indicating a general role for CARD14 in psoriasis pathogenesis." (PMID 39145956, 2024). "Familial cases of PRP are associated with mutation of the CARD14 gene, located in the psoriasis susceptibility locus 2 (PSORS2), which codifies a protein that activates the nuclear factor (NF)-кB, responsible for enabling genes involved in immune and inflammatory reactions." (PMID 39202665, 2024). "Psoriasis-associated mutations in CARD14 similarly cluster within the CARD and CC domains and we have recently demonstrated that the highly penetrant CARD14E138A psoriasis-associated mutation induces a conformational change in CARD14 that induces interaction with BCL10 and MALT1." (PMID 39145956, 2024). "This study confirms the association between two CARD14 nsSNPs, rs2066965 and rs34367357 with psoriasis in a Pakistani population, and could be helpful in identifying the role of CARD14 gene variants as potential genetic markers in patients with psoriasis." (PMID 36012602, 2022). "In fact, CARD14 maps to the PSORS2 psoriasis-associated locus." (PMID 36551948, 2022). "Furthermore, while some models have suggested pathogenic pathways common to psoriasis and atopic dermatitis, it is noteworthy that CARD14 defects with the opposite polarity to those responsible for psoriasis (i.e., LoF alleles) cause severe atopic dermatitis." (PMID 36733767, 2022). "Mechanistically, the mutations in the CARD14 gene lead to hyperinflammation in the keratinocytes, which causes immune cell infiltration, hyperproliferation of keratinocytes, and keratosis, which are typical hallmarks of psoriasis." (PMID 36012602, 2022). "The authors also suggested that MALT1 inhibitors promote the reduction of skin inflammation triggered by CARD14 gene mutant variants and therefore may possibly serve as a treatment option in psoriasis." (PMID 34445769, 2021). "Such psoriasis/PRP type V patients with CARD14 mutations are considered to be typical AiKD cases." (PMID 32153585, 2020). "Psoriasis-associated CARD14 mutations in humans are generally heterozygous." (PMID 32597759, 2020). "This presumably explains why CARD14 psoriasis-associated mutations are generally heterozygous." (PMID 32597759, 2020). "Psoriasis genome-wide association studies show CARD14 to be a risk gene for psoriasis, meaning that a CARD14-mediated pathway could be working in psoriasis patients without CARD14 mutations." (PMID 32153585, 2020). "Genetic background also contributes to the penetrance of gain-of-function CARD14 mutations in promoting psoriasis, as recently confirmed in mouse studies in which the survival of mice with a constitutive Card14E138A mutation is increased by crossing C57BL/6 mice onto a 129S4 background." (PMID 32597759, 2020). "The majority of psoriasis-associated CARD14 mutations identified are heterozygous suggesting that homozygous expression of such CARD14 mutations might exceed a threshold of NF-κB activation that is compatible with life." (PMID 32597759, 2020). "In addition, IL-23 and imiquimod treatments to induce psoriasis were shown to be unsuccessful in CARD14/CARMA2-deficient mice." (PMID 31130981, 2019).
psoriasis (continued). "A higher frequency of CARD14 variants, in particular the common p.R820W polymorphism, were found among responders to TNFα-targeted blockade, suggesting that CARD14-associated psoriasis could benefit from anti-TNF treatment." (PMID 30386326, 2018). "Finally, recent data demonstrated psoriasis associated mutations in CARMA2 (CARD14) are promoting formation of the CARMA2/CARD14–BCL10–MALT1 (CBM-2) complex to induce chronic inflammation in keratinocytes." (PMID 30022982, 2018). "Interestingly, activating mutations in the CARMA2-encoding gene CARD14 have been found to be associated with development of psoriasis, an inflammatory skin disease, in human patients." (PMID 30214442, 2018). "This hyperactivity is reduced upon MALT1 protease inhibition with mepazine, thus suggesting that MALT1 treatment could benefit patients with CARD14-associated psoriasis." (PMID 30386326, 2018). "Interestingly, mutations in the CARMA1 homologue CARMA2 (also known as CARD14) have been recently associated with the development of psoriasis in human patients." (PMID 26507244, 2016). "CARD14 was also expressed non-dermal endothelial cells, such as aortic endothelial cells, which may indicate a role of CARD14+ECs in the systemic inflammation and cardiovascular comorbidities associated with psoriasis." (PMID 25369198, 2014). "The principal components analysis (PCA) showed that the transcriptome of LS biopsies from patients with CARD14 mutations clustered close to those of LS classic psoriasis, and the NL and post-treatment biopsies of these two patients clustered close to normal and NL skin of classic psoriasis." (PMID 25369198, 2014). "Together, these observations suggest CARD14 may play a pathogenic role not only in individuals with psoriasis associated CARD14 mutations, but also in general psoriasis pathogenesis." (PMID 25369198, 2014). "Additionally, expression of CCL2 mRNA was significantly induced, and there were mild (but not statistically significant) increases in CXCL1, CXCL10, CCL5, and IL-8 in psoriasis-associated mutant CARD14 transfected HDBECs compared to wild-type HDBECs." (PMID 25369198, 2014). "In addition, a genetic study reported that the mutation of CARD14, which is mainly expressed in keratinocytes, may trigger psoriasis by NF-κB activation." (PMID 35116069, 2022). "Therefore, genetic variation of TLR4 and CARD14 genes might be the contributing risk factors for psoriasis by modulating the cellular physiological processes." (PMID 36382932, 2022). "Furthermore, CARD14 deficiency protected mice from IMQ- or IL-23-induced psoriasis-like dermatitis." (PMID 35075118, 2022). "Moreover, CARD14 gene expression was found not only in keratinocytes but also in lymphatic and aortic endothelial cells, what suggests that CARD14 mutations may contribute to the psoriasis comorbidities of cardiovascular and systemic origin." (PMID 34445769, 2021). "Interestingly however, CARD14 mutations have been observed previously in psoriasis patients." (PMID 32737342, 2020). "Gain of function dominant mutations in caspase recruitment domain family member 14 (CARD14) were found to cause plaque psoriasis in two families (30% of the members also developed psoriatic arthritis) and a monogenic form of severe generalized pustular psoriasis (CARD14-mediated psoriasis -CAMPS)." (PMID 31286971, 2019). "Furthermore, a recent GWAS meta-analysis validated CARD14 as a psoriasis risk locus." (PMID 24520335, 2014). "Hyperactivation of CARD14 specifically in keratinocytes is sufficient for the induction of the rapid development of psoriasis-like skin inflammation in mice." (PMID 41131424, 2025). "The CARD14 gene, located within the PSORS2 locus, encodes an activator of nuclear factor-κB (NF-κB) and harbors variants linked to rare and common psoriasis forms." (PMID 39859462, 2025).
psoriasis (continued). "To study the effect of CARD14 signaling in IEC, we generated mice expressing CARD14(E138A), a rare gain-of-function variant that was originally described in psoriasis patients, specifically in IEC (referred as CARD14(E138A)IEC mice)." (PMID 41131424, 2025). "Susceptibility genes (e.g., c-Rel, TRAF3IP2, and CARD14) and inhibitors (NFKBIA, TNFAIP3, TNIP1, and ZC3H12C) in the NF-κB pathway are associated with psoriasis development." (PMID 38892253, 2024). "mTORC1 activation was also discovered as a new signalling output downstream of CARD14, directly linking mTORC1 signalling in psoriasis to a key protein involved in psoriasis pathogenesis." (PMID 39145956, 2024). "The term CARD14 Associated Papulosquamous Eruption (CAPE), first proposed in 2018, describes the spectrum of conditions associated with features of psoriasis, PRP, or both, and CARD14 mutations." (PMID 39104646, 2024). "In this study, we verified the psoriasis susceptibility genes IFIH1 (2q24.3), ERAP2 (5q15), IL18R1 (2q12.1), LTBR (12p13.31), IL1RL1 (2q12.1), CARD14 (17q25.3), and SLC9A4 (2q12.1)." (PMID 36425068, 2022). "This study showed the increased risk of developing psoriasis in patients carrying SNPs in PSORS1C3, CARD14 and TLR4 genes." (PMID 36382932, 2022). "Other validated psoriasis susceptibility genes were ERAP2 (5q15), IL18R1 (2q12.1), LTB (12p13.31), IL1RL1 (2q12.1), CARD14 (17q25.3), and SLC9A4 (2q12.1)." (PMID 36425068, 2022). "Although CARD11 and CARD10 have been previously shown to contribute to lymphoid malignancies and epithelial carcinomas, respectively, CARD14 signalling has so far been mainly studied in keratinocytes in the context of psoriasis." (PMID 36009554, 2022). "Sporadic or dominant gain-of-function mutations in the CARD14 gene also activate NF-κB pathway and cause early-onset plaque psoriasis, pityriasis rubra pilaris and generalized pustular psoriasis, which have been named CARD14-mediated psoriasis (or CAMPS)." (PMID 33999387, 2021). "Here we found a SNP (rs34367357) of CARD14 carried by the proband and his mother with psoriasis after screening the candidate genes through WES." (PMID 32725812, 2020). "Among the newly identified loci, five are specifically associated with psoriasis and are involved in innate immune responses (DDX58, KLF4, ZC3H12C, CARD14 and CARM1)." (PMID 33007857, 2020). "Mice with CARD14 genetic mutations (CARD14E138A/+ and CARD14DQ136/+) were shown to spontaneously develop psoriasis-like disease due to hyper-activation of NF-κB and enhanced activation of IL-17A signaling in keratinocytes." (PMID 31130981, 2019). "Recent studies demonstrated that CARD14 variants and NFκB activation mediated by mutant CARD14 is implicated in the development of both PRP and psoriasis and its rare variants have also been implicated in the development of generalized pustular psoriasis." (PMID 30018619, 2018). "CARMA2/CARD14-deficient mice have been recently generated and found to be resistant to psoriasis induction by imiquimod cream or recombinant IL-23 injection." (PMID 30214442, 2018). "Recent publications of mouse models also helped to better understand the physiological contribution of CARD14 to psoriasis pathogenesis." (PMID 30386326, 2018). "Increasing evidence indicates that genetic mutations in genes such as TNFAIP3, TNIP1, NFKBIA, TRAF3IP2, and CARD14 result in an impaired negative regulation of NF‐κB proinflammatory activity leading to psoriasis." (PMID 28377495, 2017). "Due to the critical role of activated immune cells in psoriasis, we first determined if CARD14 co-localized with markers of various immune cell populations." (PMID 25369198, 2014). "This suggests a connection between CARD14-NF-κB activity in endothelial cells and subsequent chemokine induction in psoriasis, and a potential role for CARD14 activity within endothelial cells in the pathogenesis of psoriasis." (PMID 25369198, 2014).
psoriasis (continued). "Similar findings were observed in both classical psoriasis patients and a patient from a PSORS2-linked family (GEN001), who harbored a confirmed gain-of-function CARD14 mutation (G117S)." (PMID 25369198, 2014). "We have previously shown that keratinocyte-specific expression of CARD14(E138A) in mice leads to the development of psoriasis-like skin pathology, which is characterized by epidermal thickening and increased inflammatory cell infiltration, and cytokine expression." (PMID 41131424, 2025). "The CARD14-mTOR signalling axis may be a promising therapeutic target for the treatment of psoriasis." (PMID 39145956, 2024). "These novel findings suggest that activation of mTORC1 by CARD14 may play an important role in controlling keratinocyte proliferation in psoriasis." (PMID 39145956, 2024). "In the current study, a multi-protein CARD14 signalling complex that is induced by the psoriasis-associated CARD14E138A variant, but not by wild type (WT) CARD14, was characterized in keratinocytes." (PMID 39145956, 2024). "Except for mutations in CARD14, mutations in IL-36 receptor antagonist (IL-36RN) and adaptor-related protein complex 1 subunit sigma 3 (AP1S3) have also been identified to cause or contribute to pustular psoriasis that is a rare and severe form of psoriasis." (PMID 35075118, 2022). "In contrast to CARD10 and CARD11, CARD14-activating stimuli are still largely unclear; thus, CARD14 activation has mainly been studied in the context of CARD14 overexpression or by the use of specific CARD14 gain-of-function mutants identified from psoriasis patients." (PMID 36009554, 2022). "It has been observed that mutations of the CARD14 gene and other members of the CARD-containing membrane-associated guanylate kinase protein (CARMA) family may increase the risk of psoriasis and are also linked with CVD." (PMID 34445769, 2021). "Delineating the correlation between genotype of CARD14 and phenotype of psoriasis could contribute to our understanding of the pathogenesis of psoriasis." (PMID 32725812, 2020). "This raises the possibility that it may be feasible to develop topical medicines that block CARD14 signalling in the skin to treat CARD14-induced psoriasis and systemic inflammation." (PMID 32597759, 2020). "CARD14 is highly expressed in epidermal keratinocytes, and its mutation is detected in both familial and non-familial psoriasis." (PMID 32252279, 2020). "CARD14 was discovered to be highly expressed in keratinocytes and was identified as the causative gene at the PSORS 2 locus, which had previously been identified as one of the principle risk loci for psoriasis." (PMID 32725812, 2020). "Psoriasis-associated CARD14 mutations are not linked with inflammatory gut phenotypes, although CARD14 is also expressed at high levels in the gastro-intestinal tract in humans." (PMID 32597759, 2020). "In contrast CARD14−/− mice displayed attenuated skin inflammation in murine psoriasis models." (PMID 32737342, 2020). "Consistently, many psoriasis susceptibility genes encode the TRAF6 signaling players, such as ACT1 (TRAF3IP2), A20 (TNFAIP3), ABIN1 (TNIP1), IL-36Ra (IL36RN), IkappaBzeta (NFKBIZ), and CARD14." (PMID 31156649, 2019). "Some of the CARD14 mutations found in patients were shown to enhance NF-κB activation and promote secretion of CCL20 and IL-8, two chemokines known to be associated with psoriasis." (PMID 30214442, 2018). "This also correlated with enhanced NF-κB activity and proinflammatory gene induction, suggesting that CARD14 GoF in endothelial cells might also contribute to psoriasis pathogenesis." (PMID 30386326, 2018). "While all family members had CARD14 mutations, the PRP sufferers had an additional frame-shift mutation in DTX1, a regulator of regulatory T cells, while the psoriasis-affected individual harbored a mutation in NLRC5, a molecule that activates NF-κB but also regulates MHC-I transcription." (PMID 30386326, 2018).
psoriasis (continued). "Since the initial identification of GoF mutations of CARD14 as being responsible for psoriasis in two large kindreds and in a sporadic case of severe GPP, 44 missense, 4 splice site variants and 1 in frame deletion have been described in CARD14 in patients with several psoriatic skin disorders." (PMID 30386326, 2018). "Genetic variants of CARD14 were described to affect NFκB activation in both psoriasis and PRP; however, the level of NFκB activation does not correlate with the severity of the disease or with the disease phenotype." (PMID 30018619, 2018). "This balance between CARD10 and CARD14 might be important in the context of psoriasis where keratinocyte differentiation processes are known to be dysregulated." (PMID 30386326, 2018). "CARD14 mRNA was also differentially upregulated in lesional psoriasis in an RNAseq study." (PMID 25369198, 2014). "However, keratinocytes expressed higher levels of CARD14 compared to endothelial cells, possibly indicating a more prominent role for CARD14 in KCs than ECs in psoriasis pathogenesis." (PMID 25369198, 2014). "Similarly, CARD14+ ECs in psoriatic skin contained pNF-κB, demonstrating activation of ECs in psoriasis." (PMID 25369198, 2014). "PRP is traditionally characterized as distinct from psoriasis, and therefore it is not yet understood how CARD14 mutations can result in two disease phenotypes." (PMID 25369198, 2014). "Additionally, a SNP in CARD14 achieved genome-wide significance in a recent meta-GWAS study containing 10,588 cases of psoriasis and 22,806 controls." (PMID 25369198, 2014). "Although mild intestinal inflammation and delayed motility have not yet been reported in human psoriasis patients with hyperactivating CARD14 mutations, this may have remained unnoticed or neglected." (PMID 41131424, 2025). "Furthermore, rapamycin ameliorated CARD14E138A-induced keratinocyte proliferation and epidermal acanthosis in mice, suggesting that blocking mTORC1 may be therapeutically beneficial in CARD14-dependent psoriasis." (PMID 39145956, 2024). "Thus far, CARD14 mutations have been associated with several systemic pustular rash diseases, including generalized pustular psoriasis (GPP), palmoplantar psoriasis, psoriatic arthritis, and psoriasis." (PMID 38013380, 2023). "Additionally, CARD14 was discovered to be highly expressed in keratinocytes and was identified as the causative gene at the Psoriasis Susceptibility (PSORS) 2 locus, which had previously been identified as one of the principle risk loci for psoriasis." (PMID 30386326, 2018). "In addition, NF-κB activity is regulated by CARD14, a protein of “signalosome” complex involved in activation of innate immunity molecules (i.e., IL-36γ, CXCL8, and CCL20), whose gene shows different allelic variants associated to psoriasis." (PMID 30034395, 2018). "In other studies, genetic association between psoriasis and CARD14 is also not clear." (PMID 30386326, 2018). "Therefore, CARD14 may play an important role in psoriasis pathogenesis partially through pro-inflammatory activities within dermal endothelial cells." (PMID 25369198, 2014). "Similar to what has been observed in humans with psoriasis or PRP, NF-kB expression was higher in CARD14-overexpressing embryos compared to controls." (PMID 36551948, 2022). "In this study, SNP profiling of PSORS1C3, CARD14, and TLR4 genes in 71 patients with psoriasis and 46 healthy individuals by direct DNA sequencing was investigated to determine disease-associated SNPs." (PMID 36382932, 2022). "Similar to CARD14 gene, the role of TLR4 gene is related to the development of a number of inflammatory diseases, such as psoriasis." (PMID 36382932, 2022). "Based on the family history of psoriasis, genetic work for this case was carried out focusing on the PSORS, including CARD14 (Caspase Recruitment Domain‐containing protein 14, *607211) (also called CARMA2 or BIMP2)." (PMID 32725812, 2020).